CRP (C-reactive protein)
Diseases named in the same sentence as CRP in open-access papers (continued):
Sharing a sentence is not in itself a finding about the gene and the disease.
leukopenia (continued). "Initial laboratory findings were significant for a reactive HIV antibody screen, leukopenia (white blood cell (WBC) count of 4.3 × 10^9/L), and an elevated C-reactive protein (CRP) of 64 mg/L." (PMID 40605901, 2025). "Laboratory tests at admission revealed hyperinflammation, with elevated C-reactive protein (CRP) at 331.0 mg/L (reference value < 5 mg/L), procalcitonin at 130 mg/L, and leukopenia at 2.1 × 109/L." (PMID 40981018, 2025). "In this series of cases, all patients showed higher levels of CRP, PCT, and D-dimer at admission, in addition to leukopenia." (PMID 37368363, 2023). "His CRP, PCT, ESR, and SF were elevated, along with macrocytic anemia (Hb 66 g/L and MCV 120.1 g/L) and mild leukopenia (WBC 3.22*109/L)." (PMID 35547205, 2022). "We have proposed an SFTS prediction scoring system including leukopenia (WBC count < 4000/μL), aPTT prolongation (>40 s), normal CRP level (≤3.0 mg/dL), and elevated CK level (>1000 IU/L) to differentiate SFTS from scrub typhus." (PMID 35632834, 2022). "Increased levels of D-dimer, ferritin, lactate dehydrogenase (LDH), and C-reactive protein (CRP) and leukopenia have been identified as laboratory biomarkers of severity." (PMID 34888199, 2021). "The other one case was excluded because only leukopenia was present on the initial visit day (WBC 1,880/mm3, platelet 110,000/mm3, CRP 2.73 mg/dL) which was 4th day of illness." (PMID 32134948, 2020). "Some biomarkers, such as CRP, LDH, leukopenia, and hypoxemia have been considered as predictors for severe illness by influenza A/H1N1 virus." (PMID 23148654, 2012). "Fever (38.7°C), elevated C-reactive protein (CRP) level (235 mg/L), leukopenia (3.2 × 109/L) and thrombopenia (73 × 109/L) were found." (PMID 20441600, 2010). "The lab findings revealed leukopenia and elevated levels of ESR and CRP." (PMID 41847937, 2026). "In the current study, it was revealed that individuals belonging to the non-survival group exhibited a higher tendency of CRP levels and leukopenia." (PMID 39103964, 2024). "In addition, fever upon triage, leukopenia, WBC count, hemoglobin level, albumin level, blood glucose, HbA1c, CRP, and ESR also showed significant differences between IFS and NIFS patients." (PMID 36547572, 2022). "In addition, some hematological changes were observed: lymphocytopenia (64.5%), increased C-reactive protein (CRP) (44.3%), increased lactic dehydrogenase (DHL) (28.3%), and leukopenia (29, 4%)." (PMID 33524039, 2021). "Compared to patients without cancer, cancer patients tended to have leukopenia and elevated high-sensitivity C-reactive protein (hs-CRP) and procalcitonin." (PMID 33995633, 2021). "Furthermore, the differential diagnosis of SFTS was significantly associated with the presence of gastrointestinal symptoms (AUC 0.95), the absence of a skin rash (AUC 0.98), leukopenia <3.7 × 109/L (AUC 0.95), and low CRP levels < 1.66 mg/dL (AUC 0.98) (p < 0.001 for each factor)." (PMID 38004073, 2023). "A retrospective Japanese study suggested that a normal CRP level alone could be used to clearly distinguish SFTS from JSF and that the absence of rash and leukopenia may aid in diagnosis." (PMID 40922296, 2025). "Laboratory clues-such as markedly elevated CRP and preserved or elevated WBC (rather than leukopenia), presence of rash including involvement of palms/soles, and eschar-may point to JSF." (PMID 41376761, 2025).
psoriasis (275 papers, 2010 to 2026). An autoimmune condition characterized by red, well-delineated plaques with silvery scales that are usually on the extensor surfaces and scalp. "Genetic data from Mendelian randomization suggest a potentially causal relationship between CRP and HF development, lending biological plausibility to our observed associations between systemic inflammation and myocardial dysfunction in psoriasis." (PMID 41280408, 2025). "Adiponectin and c-reactive protein (CRP) were assessed as inflammatory markers—increased levels were usually associated with the severity of psoriasis." (PMID 37375611, 2023). "It has been stated that CRP elevation, which is considered an independent cardiovascular risk factor, is associated with psoriasis and psoriatic arthritis." (PMID 37731441, 2023). "In a study, it was shown that the incidence of carotid atherosclerotic plaque in psoriasis patients was higher than in the control group, associated with an increase in inflammatory parameters such as CRP and ESR." (PMID 37731441, 2023). "As a marker of systemic inflammation, C-reactive protein (CRP) has been proposed to predict the risk of CAD among psoriasis patients." (PMID 36323703, 2022). "On the other hand, the supplementation of Bifidobacterium species, which belong to the Actinobacteria, caused a decrease in the serum concentration of TNFα and C-reactive protein (CRP) in psoriasis patients." (PMID 33924414, 2021). "Systemic inflammation, which causes persisting symptoms of psoriasis, has several indicators, for example, serum level of CRP, HDL-cholesterol, and Apolipoprotein-A-I." (PMID 34207504, 2021). "In recent years, RDW elevation has also been described in patients with psoriasis and has been associated with psoriasis severity and with biomarkers of inflammation such as C reactive protein (CRP)." (PMID 33776570, 2021). "We carried out a retrospective observational study aimed at assessing RDW values in psoriatic patients and its association with psoriasis severity and C reactive protein (CRP)." (PMID 33776570, 2021). "Psoriatic patients had a statistically significant increase of CRP, associated with the inflammatory nature of the disease, and, as known, the prognostic significance CRP has for the course of psoriasis." (PMID 34209865, 2021). "It has been demonstrated that clearance of psoriasis by phototherapy is associated with decreased acute inflammatory markers such as serum C-reactive protein (CRP) levels." (PMID 33812333, 2021). "Psoriasis, which is known to have a significantly higher risk of associated HDs, is associated with higher C-reactive protein (CRP) levels." (PMID 33961663, 2021). "Raised CRP levels were significantly associated with sacroiliitis, and longer time of psoriasis was predictive of chronic sacroiliitis lesions." (PMID 32665619, 2020). "Elevated C-reactive protein, monocyte-to-high-density-lipoprotein ratio, neutrophil-to-lymphocyte ratio, and monocyte-to-lymphocyte ratio were significantly associated with psoriasis." (PMID 31889591, 2020). "In the present study, CRP levels were also higher in patients with psoriasis and were found to be associated with the PASI score." (PMID 31889591, 2020). "Raised CRP levels were significantly associated with sacroiliitis, and the time of psoriasis was predictive of chronic sacroiliitis lesions." (PMID 32665619, 2020). "CRP levels were higher among sacroiliitis patients (p = 0.028), and time of psoriasis was positively associated with chronic lesions (p = 0.006)." (PMID 32665619, 2020). "Baseline grade of sacroiliitis, presence of psoriasis, and CRP elevation were significantly associated with inflammatory SPARCC score of SIJ." (PMID 30947732, 2019). "Baseline sacroiliitis severity, psoriasis, and CRP elevation had positive association in univariate and multivariate regression analysis for SIJ inflammatory SPARCC score." (PMID 30947732, 2019).
psoriasis (continued). "In the same study, the authors reported a statistically significant increase of salivary C-reactive protein (CRP), associated with the inflammatory nature of the psoriasis, and, as known, CRP has a prognostic significance for the worsening of psoriasis." (PMID 29888276, 2018). "Patients with psoriasis have elevated levels of C-reactive protein (CRP), which has been independently associated with an increased risk of CVD." (PMID 29662733, 2018). "Circulating A-SAA levels are correlated with those of CRP, which has been reported to be associated with psoriasis severity." (PMID 28708859, 2017). "Recent data provided by our group demonstrated that there was a significant association the adherence to the MD with the severity of psoriasis, and CRP levels." (PMID 27455297, 2016). "CRP has been shown to be associated with all-cause mortality in chronic immune-mediated inflammatory disease, including psoriasis and to correlate with risk of cardiovascular events in patients who have instituted aggressive statin therapy." (PMID 27448600, 2016). "The high amounts of circulating inflammatory biomarkers, such as CRP and IL-22, which were streamed from skin lesions into the bloodstream, may serve to explain the association between the severity of psoriasis and respiratory disorders." (PMID 40005314, 2025). "Evaluation of the NLRP3 gene polymorphism, the serum level of CRP and TNFα in psoriasis patients and assessment of the NLRP3 (rs10754558) gene polymorphism, CRP and TNFα with disease severity and their role as biomarkers for response to Methotrexate and Adalimumab in psoriasis." (PMID 38965465, 2024). "Moreover, BMI, SBP, CRP, and uric acid were significantly associated with psoriasis, but waist circumference, blood glucose, serum lipids, DBP, and creatinine were not." (PMID 39200903, 2024). "The results showed that the PASI (Psoriasis Area and Severity Index) score, measured for the severity status of psoriasis, presented a significant association with the percentage of the C-reactive protein levels, which was negatively correlated with adherence to the Mediterranean diet." (PMID 35889927, 2022). "Serum CRP levels and complete blood count-derived biomarkers, such as NL and PL, have been associated with disease severity and joint involvement in patients with psoriasis." (PMID 32881431, 2020). "Although the pathogenesis of psoriasis is still not fully understood, psoriasis is associated with markers of systemic inflammation, such as increased C-reactive protein levels and T-helper cell type 1 (TH1) cytokines, and inflammatory processes and oxidative stress are frequently delineated." (PMID 23653531, 2013). "After ruling out any secondary causes of renal disease, fifty individuals with verified psoriasis were included, and they came to the following conclusion: The inflammatory milieu was implicated by the positive connection between renal involvement and high-sensitivity CRP (hs-CRP)." (PMID 36381899, 2022). "FAPI-positive psoriasis patients had significantly higher body mass index (BMI) (p=0.036) and Disease Activity Score 28-C reactive protein (p=0.033) compared with FAPI-negative patients." (PMID 41871918, 2026). "Probiotics are associated with significantly reduced Psoriasis Area and Severity Index (PASI) scores, increased PASI 75 response rates, lowered inflammatory biomarkers (CRP, TNFα, IL-6) and improved Dermatology Life Quality Index (DLQI)." (PMID 42005309, 2026). "It was found that Hs-CRP and Siglec-14 decreased in all patients after treatment, Hs-CRP decreased more significantly in mild psoriasis patients, and Siglec-14 decreased in both mild and moderate-severe groups (p < 0.05)." (PMID 41598424, 2026). "We found that PsA patients with hyperuricemia had higher age, BMI, DAPSA score, ESR, CRP, serum cholesterol and triglycerides, and longer duration of psoriasis and psoriatic arthritis than PsA patients with normal serum uric acid levels." (PMID 40192998, 2025).
psoriasis (continued). "One of the observed anti-inflammatory effects of semaglutide is the effect on the reduction of CRP, which can be used as a parameter of the disease course and the psoriasis prognosis, but additional research is necessary to fully clarify this mechanism." (PMID 39858442, 2025). "Decisions about biological therapy initiation include assessment of levels of biomarkers (CRP, Calprotectin), endoscopic activity, existing arthropathies and skin manifestations (like psoriasis)." (PMID 41398905, 2025). "Thirdly, elevated levels of inflammatory markers like ESR and CRP were observed in psoriasis patients, further approving the inflammatory background of this dermatosis." (PMID 40650250, 2025). "Clinical disease activity improved significantly, with zero tender and swollen joints, CRP of 1.3 mg/l, and psoriasis body surface area 0%." (PMID 40152236, 2025). "CRP levels possess the capability to be a simple and inexpensive marker for determining the inflammatory status in psoriasis patients and demonstrating a higher inflammatory load as compared to healthy individuals." (PMID 40563994, 2025). "Our research aimed to investigate NLR, PLR, SII, and CRP levels in patients with psoriasis treated with biological drugs." (PMID 40332589, 2025). "In contrast, psoriasis showed BMI-independent CRP elevation, suggesting that adiposity and cardiometabolic factors alone do not fully account for the level of systemic inflammation." (PMID 41280408, 2025). "Significant reduction in plasma CRP levels across all patient groups.TNF-α levels decreased significantly in psoriasis patients.Demonstrated systemic anti-inflammatory effects beyond the gut." (PMID 41277234, 2025). "Analyzing the correlations in our study, we confirmed some expected relationships: a significant positive correlation between psoriasis duration and BMI (r = 0.39, p < 0.05) and, additionally, between BMI and C-reactive protein (r = 0.4, p < 0.05)." (PMID 40137160, 2025). "Studies have shown that adherence to this diet correlates with lower psoriasis severity and a decreased systemic inflammatory burden, as measured by markers like C-reactive protein (CRP) and cytokine profiles." (PMID 40243475, 2025). "This study aims to address this gap by evaluating the change in NLR, PLR, SII, and CRP (C-reactive protein) in patients with psoriasis undergoing biological treatment and exploring their potential to differentiate between biologic agents." (PMID 40332589, 2025). "In the same study, the authors reported a statistically significant increase in salivary C-reactive protein (CRP) levels, consistent with the inflammatory nature of psoriasis." (PMID 40731810, 2025). "The serum uric acid levels were significantly positively correlated with age, duration of Psoriasis, duration of PsA, BMI, CRP, ESR, DAPSA, and PASI score." (PMID 40192998, 2025). "While classical biomarkers such as CRP and IL-6 are widely used in psoriasis-related research and clinical monitoring, each has limitations." (PMID 40722707, 2025). "At baseline, the patient’s DASs included 3 tender and swollen joints, CRP 3.6 mg/l and psoriasis skin body surface area of 3%." (PMID 40152236, 2025). "In patients with psoriasis, an autoimmune, inflammatory skin disorder, we recently demonstrated that CRP and SAA, as well as markers of T cells mediated inflammation were associated with larger LV mass index." (PMID 41141372, 2025). "Because the C-reactive protein (CRP) is recognized to have a predictive value for the progression of psoriasis and is connected with the inflammatory character of the illness, its statistically significant elevation in psoriatic individuals is not surprising." (PMID 40005360, 2025). "SF was positively correlated with Psoriasis Area Severity Index, C-reactive protein, and disease duration, with statistically significant differences." (PMID 41204483, 2025).
psoriasis (continued). "The correlations between NLR, PLR, and SII and different variables were investigated, followed by conducting ANOVA for repeated measures for age, sex, psoriasis duration, initial CRP, or prior exposure to biological drugs." (PMID 40332589, 2025). "Elevated levels of inflammatory markers like ESR and CRP were observed in psoriasis patients, with p less than 0.001, further supporting the inflammatory nature of the disease." (PMID 40650250, 2025). "Systemic inflammation in psoriasis, higher levels of C-reactive protein, and pro-inflammatory cytokines like interleukin-17, interleukin-23, and interleukin-36 are thought to play a role in both skin and lung inflammation and the airway remodeling pathway." (PMID 40005314, 2025). "The average CRP level in the psoriasis group (25.75 ± 18.29 mg/mL) was also significantly higher than that in the control group (6.24 ± 3.31 mg/mL)." (PMID 41204483, 2025). "More severe forms of psoriasis are conditions of high inflammation, which is confirmed by the clinical picture and numerous inflammatory parameters such as C-reactive protein (CRP), cytokines and homocysteine, which vary with disease activity." (PMID 39858442, 2025). "The present study observed a statistically significant elevation in serum hs-CRP levels among psoriasis patients relative to healthy controls, consistent with findings from a previously conducted investigation." (PMID 39104857, 2024). "Spearman’s correlation showed statistically significant positive correlation for NLR and PLR (rs = 0.52, p < 0.0001), as well as for WBC and CRP (rs = 0.49, p < 0.001) in psoriasis patients." (PMID 38127137, 2024). "With the improvement in the clinical severity of psoriasis, the serum CRP level in the probiotic group decreased more significantly than that in the placebo group." (PMID 39328313, 2024). "In our study, only hs-CRP serum levels in psoriasis patients were significantly higher than in healthy controls." (PMID 39104857, 2024). "Prior studies have consistently shown elevated CRP levels in patients with psoriasis compared to healthy controls." (PMID 39202262, 2024). "They reduce C-reactive protein levels and inhibit tumor necrosis factor-alpha and interleukin-1 and -6, which have an important role in the pathogenesis of psoriasis." (PMID 39120229, 2024). "Herein, we have investigated several redox homeostasis biomarkers (i.e., MDA, AOPP, CAT), inflamation (i.e. CRP) and metabolic parameters (i.e., fasting glucose, lipid parameters, liver enzymes and renal function markers) in relation to psoriasis severity." (PMID 38496030, 2024). "In various clinical trials, probiotics have been shown to significantly improve the severity of skin lesions and quality of life in psoriasis patients, and reduce levels of inflammatory markers such as high-sensitivity C-reactive protein(hs-CRP) and IL-6." (PMID 39170985, 2024). "Our finding that BMI, SBP, CRP, and uric acid were elevated in psoriasis patients is consistent with previous studies." (PMID 39200903, 2024). "There was highly statistically significant variance between psoriasis patients and controls as regards serum CRP and TNFα levels (P < 0.00001)." (PMID 38965465, 2024). "The findings indicated that TNF-α inhibitors more effectively reduced coronary inflammation, evidenced by significant reductions in CIMT, coronary plaques (measured by CCTA), CRP, and Psoriasis Area and Severity Index (PASI) scores compared to phototherapy." (PMID 39739136, 2024). "The meta-analysis revealed that psoriasis patients had a significantly increased serum CRP level than the control group (MD 0.87, 95% CI 0.37 to 1.37, 5 studies, 627 participants, I2 = 87%, p = 0.0007)." (PMID 39200903, 2024). "A highly statistically significant difference between psoriasis patients and controls was noted as regards serum CRP and TNFα levels (P < 0.00001)." (PMID 38965465, 2024).